MAPK15 (mitogen-activated protein kinase 15)
Diseases named in the same sentence as MAPK15 in open-access papers (continued):
Sharing a sentence is not in itself a finding about the gene and the disease.
tumor (21 papers, 2013 to 2025). "Previous studies have shown that MAPK15 influences tumour cells’ migratory and invasive capabilities via modulating the MMPs pathway." (PMID 39866235, 2025). "The inhibition of MAPK15 reduces cell proliferation and the tumor development produced by the Philadelphia chromosome, presenting MAPK15 as a therapeutic target in CML." (PMID 40227235, 2025). "MAPK15 was distributed mainly in the cytoplasm of tumor cells, but was expressed in the nucleus as well." (PMID 38203280, 2023). "In this context, we have already shown both in vitro and in vivo that overexpression of MAPK15 gives a proliferative advantage to tumor cells." (PMID 35642724, 2022). "As the tumor-sphere assay allows the enrichment of potential MB-initiating cells, we compared MAPK15 expression in adherent cells and in spheres derived from DAOY, UW228, and ONS-76 cells, by qPCR." (PMID 34638386, 2021). "MAPK15 is a novel HuR kinase that regulates tumor suppressor PDCD4 through a miR-21 dependent mechanism." (PMID 30524968, 2018). "To confirm, in vivo, a pro-tumorigenic role for MAPK15 overexpression in human EC, we took advantage of the best-characterized cell line derived from this kind of tumor, namely NTera2/D1 cells, and used it in classical xenograft experiments." (PMID 26988910, 2016). "Ultimately, we provide evidences that MAPK15-dependent autophagy is necessary for the control of DNA damage and for tumor formation in this context." (PMID 26988910, 2016). "DNA copy number of MAPK15 in six samples (268-1, 271-1, 272-2, 301-1, 685-1 and 685-2) with available tumor and matched normal tissues among the 40 samples was analyzed by multiplex ligation-dependent probe amplification (MLPA)." (PMID 26035356, 2015). "In addition, lab work will identify biomarkers specific for a broader spectrum of cells like LOX, LOXL2, and MAPK15 to reveal cells with invasive phenotypes in the primary tumor and circulation." (PMID 39329988, 2024). "MAPK15 is therefore able to promote tumor growth, in vivo, in GCT models." (PMID 26988910, 2016). "Ultimately, we reasoned that, if autophagy represents an important consequence of MAPK15 overexpression for tumorigenesis, then the autophagy-deficient MAPK15_AXXA mutant would confer no advantage for tumor growth in xenograft assays." (PMID 26988910, 2016). "Moreover, we show that the ability of MAPK15 to control the autophagic process is necessary for basal management of DNA damage and for tumor formation controlled by the kinase." (PMID 26988910, 2016). "Copy number gains of MAPK15 were found in 15 (17%) of 88 tumor tissues." (PMID 26035356, 2015). "Previous studies have demonstrated that Trop2 promotes tumor progression, metastasis and therapy resistance through multiple signaling pathways including ERK/MAPK15, PI3K/AKT16, and Wnt/β-catenin." (PMID 41100061, 2025). "MAPK15 has also been found to interact with autophagy-related proteins such as GABARAP and LC3 to control tumor development." (PMID 36900191, 2023). "Other clinical–pathological parameters such as age, gender, depth of tumor invasion, distant metastasis, and tumor differentiation were not significantly correlated with the expression of MAPK15." (PMID 36900191, 2023). "This suggests that silencing of MAPK15, besides reducing CSC self-renewal in vitro, negatively affects also proliferation and/or survival of more differentiated neural progenitors that constitute the bulk of tumor-spheres." (PMID 34638386, 2021). "The molecular function activities; MAP kinase activity, retinol binding and RNA polymerase II activating transcription factor binding, enriched by the upregulated genes MAPK15, STRA16 and NHLH2, respectively, are activities that promote tumor cell proliferation." (PMID 33245713, 2020).
tumor (continued). "Interestingly, we have recently demonstrated that MAPK15 mediates BCR-ABL-induced autophagy and regulates oncogene-dependent cell proliferation and tumor formation." (PMID 26988910, 2016).
infection (1 paper, 2019). The state of being infected such as from the introduction of a foreign agent such as serum, vaccine, antigenic substance or organism. "In particular, some genes involved in immune/inflammatory responses and infection (e.g., IL19, MAPK15, and SERPINB10) and components of a complement system (e.g., C4B, VTN, BDKRB1, and C4BPA) have not been previously reported regarding their expression and functions in human omental adipose tissue." (PMID 30816281, 2019).
MAPK15 also shares sentences with these, for which no sentence is quoted: adenocarcinoma (2 papers); benign tumor (2); breast tumors (2); squamous cell carcinoma (2); basal cell carcinoma (1); corticotrope adenomas (1); germ cell tumors (1); hematologic malignancies (1); Hepatic steatosis (1); invasive ductal breast carcinoma (1); leukemia (1); nonseminomatous germ cell tumors (1); prostate carcinoma (1); small cell carcinoma (1); teratoma (1); testicular cancer (1).